TNF (tumor necrosis factor)
Diseases named in the same sentence as TNF in open-access papers (continued):
Sharing a sentence is not in itself a finding about the gene and the disease.
dementia (continued). "Consistently, elevated peripheral pro-inflammatory cytokines (IL-1β, TNF-α, IL-2) have been reported in dementia patients." (PMID 41291751, 2025). "Plasma biomarkers in dementia showed higher amyloid beta 40, phosphorylated tau181, neurofilament light chain, and tumor necrosis factor alpha levels." (PMID 41085166, 2025). "The study also observed an improvement in TNF-α and interleuquine-1b levels, which have been related to dementia in aged individuals." (PMID 38337652, 2024). "Elevated levels of interleukin (IL)-6 and -1β, as well as tumor necrosis factor alpha (TNF-α) were found in elderly individuals’ blood samples who had a first-degree relative with dementia." (PMID 38263227, 2024). "Recently, the results of an animal study showed that hypoxia induces AD-like dementia symptoms, e.g., memory dysfunction via the dysregulation of seladin-1 and Tuj1 in the hippocampal region correlated with enhanced serum levels of TNF-α and IL-1β." (PMID 37605722, 2023). "TNF remained associated with higher risks of incident dementia in the ε4 stratum and CXCL1 was associated with higher risks of incident dementia in the ε3 stratum." (PMID 37584418, 2023). "Closely linked with the cholesterol metabolism, neuroinflammation is also a key component of AD and a recent GWAS identified the tumor necrosis factor α (TNFα) signaling pathway as a central genetic etiology of AD and related dementias." (PMID 36983062, 2023). "TNF-α has been found in animal models to promote neuronal death by activation of microglia, exacerbating dementia." (PMID 38098004, 2023). "Several studies report that patients with RA and systemic inflammatory diseases treated with TNF-α blocking agents reduce the probability of emerging dementia compared with the general population." (PMID 38201258, 2023). "For example, few reports showed that TNF-α levels in the CSF were higher than in sera among subjects with dementia, suggesting an intrathecal synthesis of this cytokine." (PMID 35486344, 2022). "The effects of QZZD on mice with dementia were determined by the levels of protein expression of core targets in the TNF inflammatory signaling pathway in hippocampal tissue." (PMID 36340795, 2022). "Focused randomized clinical trials are warranted in order to establish the efficacy of anti-TNF agents and their mechanisms of action in most common types of dementia." (PMID 36230921, 2022). "Kaplan-Meier analysis was used to display the associations of CSF TNFα, TNFR1 and TNFR2 levels with conversion to dementia among MCI individuals." (PMID 36288380, 2022). "So far, insufficient data exists on the use of TNF antagonists in dementia prevention and treatment." (PMID 36230921, 2022). "Among various cytokines involved in the immune response, tumor necrosis factor (TNF) is considered to play a significant upstream role in dementia pathology on a molecular level." (PMID 36230921, 2022). "This study aimed to evaluate the effect of epistasis of gene cytokines such as interleukin (IL)-α, IL-6, tumor necrosis factor (TNFα), and interferon-gamma (IFN-γ) on the susceptibility to the development of dementia." (PMID 36389080, 2022). "We investigate the combinatorial effect of four (IL-1α, IL-6, TNFα, and IFN-γ) genetic polymorphisms involved in the inflammatory processes of microglial cells in the brain on the susceptibility to dementia in Mexican individuals." (PMID 36389080, 2022). "Levels of TNFα in blood and CSF were increased in patients with AD dementia or other forms of dementia." (PMID 36288380, 2022). "TNF, a key pro-inflammatory cytokine, plays a central role in the pathology of several types of dementia." (PMID 36230921, 2022). "Bacopa monniera decreases intra-neuronal protein aggregation and lipofuscin accumulation and prevents microglia from secreting pro-inflammatory cytokines (IL-6 and TNF-α) in aging and dementia models." (PMID 35893883, 2022).
dementia (continued). "As shown in survive curve, there was a significant difference in rates of conversion to dementia between three groups (tertiles of TNFα levels) among MCI individuals (p = 0.024)." (PMID 36288380, 2022). "In Mexico, less has been explored about the relationship of the genes’ pro-inflammatory cytokines released from activated microglia (IL-1α, IL-6, TNFα, and IFNγ) with dementia." (PMID 36389080, 2022). "It is proved in the present study that expression levels of IL-6, CRP and TNF-α proteins in VD patients are higher than those in the normal population on one hand, and positive correlated to dementia degrees on the other hand." (PMID 34475939, 2021). "Elevated serum TNF-α is confirmed in both patients with VD and VD rat models, and it is closely related to the degree of dementia and prognosis of patients." (PMID 34912208, 2021). "A similar finding was observed in elderly individuals with dementia where an increased level of TNFα molecule was positively correlated with sTNFRII, IL-6, and C-Reactive Protein." (PMID 31178745, 2019). "The article reviews the potential role of inflammatory markers such as TNF-α in predicting dementia and/or cardiovascular disease." (PMID 29487525, 2018). "Reports also show that dementia is related to peripheral pro-inflammatory factors released by periodontal inflammatory mediators such as C-reactive protein, IL-6, haptoglobin, TNF-α, and fibrinogen." (PMID 29740354, 2018). "The involvement of cytokines in dementia is supported by studies showing that the levels of pro-inflammatory cytokines [e.g., tumor necrosis factor alpha (TNF-α), interleukin (IL)-1α, IL-1β, IL-6, and IL-8] are altered." (PMID 30510525, 2018). "Increased expression and release of TNF by microglia often occurs early in neurodegenerative diseases such as PD and human immunodeficiency virus-induced dementia and appears to be important for subsequent glial reactivity." (PMID 28476157, 2017). "Previous findings have shown higher peripheral levels of inflammatory markers such as IL-6, CRP, TNF-α in patients with dementia compared to controls." (PMID 28798686, 2017). "Additionally, elevated TNFα and IL-1β have been observed in the CSF of PLWH with HIV-associated dementia (HAD), two cytokines with the capacity to both induce neuronal injury via release of neurotoxic molecules, including ceramide and L-cysteine." (PMID 40588746, 2025). "Recent studies have shown that high levels of circulating C-reactive protein, IL-1, IL-6, tumor necrosis factor-α (TNF-α), and CD4 + T-cell count might increase the risk of dementias." (PMID 40791247, 2025). "Recognized as an integral component of brain clearance, the glymphatic system's reduced flow fails to eliminate metabolic wastes, including accumulated inflammatory cytokines like ILs and TNFα in the cerebral nerve system, which could contribute to dementia." (PMID 38779749, 2024). "If considering treatment resistance and consistent evidence via meta-analysis of cytokine change in MDD and dementia, only IL6, TNF, and CRP are implicated, though this may reflect the relative popularity of these molecules for study." (PMID 38175420, 2024). "Elevated levels of circulating inflammatory markers such as IL-6, TNFα and CRP, induces the development of chronic low-grade inflammation which has been identified as a risk predictor for several diseases such as T2DM and dementia." (PMID 37720640, 2023). "The present study suggested a potential non-linear relationship between CSF TNFα levels and the risk of development of dementia." (PMID 36288380, 2022). "In addition to reversing cell cycle arrest, BM also reduced intra-neuronal protein aggregation and lipofuscin accumulation, and it prevented microglia from secreting pro-inflammatory cytokines (IL-6 and TNF-α) in aging and dementia models." (PMID 35893883, 2022).
dementia (continued). "Our data highlight the importance of TNFα in the pathogenesis of AD and suggest that CSF TNFα could be used to predict subsequent conversion to dementia among MCI subjects." (PMID 36288380, 2022). "Our study suggested a potential non-relationship between CSF TNFα levels and the risk of development of dementia among MCI older people." (PMID 36288380, 2022). "In addition, the peripheral levels of several inflammatory cytokines, including interleukin (IL)-1, IL-6, and tumor necrosis factor (TNF)-α are often elevated in patients with dementia." (PMID 34630044, 2021). "Cell destruction by phagocytosis, membrane attack complex (MAC) by opsonizing component markers, as well as the proinflammatory cytokines (IL-1, IL6, TNF-α, and interferon-γ) produced by these innate immune responses affect the disease progression and severity of dementia." (PMID 33711047, 2021). "Future studies will determine whether this imbalance represents an early, Aβ-independent pathway leading to dementia and may reveal the AD-modifying therapeutic potential of TNF-α inhibition in the central nervous system." (PMID 33434745, 2021). "However, biological therapies, such as tumor necrosis factor (TNF) inhibitors, can lower the risk of dementia." (PMID 32489719, 2020). "In support of this mechanism, evidence from a growing number of longitudinal studies suggests that markers of systematic inflammation, such as tumor necrosis factor, nitric oxide synthase, and interleukin IL-1β, IL-6, and IL-18, are involved in the pathogenesis of dementia." (PMID 32651320, 2020). "Also consistent with our findings, one review of 118 mostly cross-sectional studies noted that the strongest evidence for upregulation of TNF-α is from studies comprised of people with mild AD dementia." (PMID 31555121, 2019). "Both MCI groups had lower levels of TNF-alpha than the control or dementia groups." (PMID 29248892, 2018). "Interestingly, however, TNF inhibitors have been recently proposed as a repurposed therapy for dementias such as AD." (PMID 30524237, 2018). "Higher serum TNFα concentrations have been reported in AD and dementia." (PMID 29358916, 2017). "In addition, activation of microglia was observed around the cranial nerves, and the levels of peripheral inflammatory cytokines, such as interleukin (IL)-6, tumor necrosis factor (TNF), IL-1, IL-10, and C-reactive protein, were increased in both dementia and PD patients." (PMID 36275822, 2022). "Our present study found that compared to the first tertile of CSF TNFα levels, the second tertile progressed faster to dementia while the third tertile did not, suggesting a potential non-linear relationship between CSF TNFα levels and the risk of development of dementia." (PMID 36288380, 2022). "Moreover, it has been shown that through astrocytes, SDF-1 inductions of TNF-α provides a course of soluble cytotoxic factors that could induce neuronal cell death and contribute to the pathogenesis of HIV associated dementia." (PMID 29487525, 2018). "Elevated levels of proinflammatory agents (cytokines), such as interleukin IL-1β, Tumor Necrosis Factor Alpha (TNF-α), and C-reactive protein, have been observed in dementia patients, with the distinctive feature that these levels worsen with age." (PMID 40231144, 2025). "mRNA of both cytokines TNF‐α and IL‐1β showed significant up‐regulation in HAD brains compared with non‐dementia HIV/AIDS patients." (PMID 38282400, 2024). "In clinical and pre-clinical models of dementia and AD, neuroinflammatory mediators such as the COX enzyme and pro-inflammatory cytokines, including TNF-α, IL-6, IL-1α, and IL-1β, trigger the nervous system’s inflammatory responses." (PMID 36840284, 2023). "In previous studies, elevated peripheral vascular cell adhesion molecule-1, tumor necrosis factor (TNF)-α, IL-2, IL-6, IL-18, and interferon-γ were found in patients with mild AD, suggesting that cytokine signaling might play a role in the intermediate stages of dementia." (PMID 35069588, 2021).
dementia (continued). "However, other authors speculated TNF-α to be neuroprotective in patients with dementia." (PMID 32802484, 2020). "The release of cytokines, such as interleukin (IL)-6 and tumor necrosis factor (TNF)-α, by microglia play important roles in the pathogenesis of dementia." (PMID 31096580, 2019). "As such, evidence for roles of IL-1β and TNF-α in surgery-induced contextual fear-conditioning deficits mimic those previously observed after LPS or Escherichia coli challenges in the same behavioural paradigm and may be more relevant to acute dysfunction than dementia." (PMID 25802557, 2015). "In comparison to other dementias (AD or CJD), MS and controls, we observed an elevated level of proinflammatory cytokines (IL-6, IL-13, TNF-α and G-CSF) specifically in the serum of rpAD patients." (PMID 25315814, 2014). "Decreased in patients with dementia. miR-223 level correlated with Mental State Examination (MMSE) scores, Clinical Dementia Rating (CDR) scores, magnetic resonance spectroscopy (MRS) spectral ratios, and serum concentrations of IL-1b, IL-6, TNF-α, and CRP." (PMID 40943171, 2025). "In other words, a phase II, double-blind, randomized study showed that weekly subcutaneous injections of TNFα(Etanercept) in a tiny number of mild to moderate AD dementia patients had no significant results as compared with placebo." (PMID 38681666, 2024). "Unexpectedly, inflammatory markers, CRP, IL-1β, IL-6, and TNF-α did not discriminate dementia cases from non-cases." (PMID 37605096, 2024). "Several included studies have demonstrated that administering whichever of 5-aminosalicylic acid, thiopurines, glucocorticoids, biologic agents, and anti-TNF therapy has a protective effect against the development of neurodegenerative diseases in patients with IBD, ranging from AD, PD, and dementia." (PMID 38720896, 2024). "Previous studies have verified that immune episodes after surgery trigger the release of pro-inflammatory cytokines from microglia, including tumor necrosis factor-α (TNF-α) and interleukin-β (IL-β), which correlates to more severe forms of dementia and AD pathogenesis." (PMID 37170230, 2023). "As blood sTNF-R1 is detectable for prolonged periods, it has been proposed to be a more reliable indicator of circulating TNF concentrations than TNF itself, suggesting potential utility as a promising inflammatory biomarker for individuals with CSVD and dementia." (PMID 36979460, 2023). "Inflammatory markers such as tumor necrosis factor (TNF), interleukin-6 (IL-6), chitinase-3-like protein 1 (CHI3L1 or YKL-40), and acute phase C reactive protein (CRP) were found to have effects on the brains or peripheral regions of dementia patients." (PMID 37873875, 2023). "When analysing the data only in this sub-sample, TNF and IFN-gamma showed weak and not statistically significant associations with all three dementia outcomes." (PMID 36085081, 2022). "Our findings suggest a FG-induced TNFα-non-cell autonomous microglial-neuronal ER stress mediated pathway with implications for early signaling cascades activated in inflammatory-mediated dementias such as AD." (PMID 30524237, 2018). "Elevated CSF HIV 1 RNA along with raised MCP-1 or neopterin suggest AIDS-dementia complex or HIV -1 encephalitis.Proviral HIV DNA within peripheral blood mononuclear cellsprognostic marker for ADC (AIDS-dementia complex).Monocytes showing increased expression of CD69, CD16, & TNF alpha." (PMID 21811520, 2010). "Additionally, neuroinflammation plays a significant role in developing dementia and AD, which implies high TNF-α levels at baseline in both pain and no pain patients." (PMID 33915996, 2021). "Meanwhile, we investigate the associations between IgG N-glycan profiles and inflammation factors including anti-inflammatory (IL-4 and IL-10) and proinflammatory factors [IL-1β, IL-6, CRP, TNF-α, and interferon-gamma (IFN-γ)], which may further explain the role of IgG glycosylation in dementia." (PMID 33542243, 2021).
dementia (continued). "Furthermore, we analyzed the association between IgG N-glycome and markers of inflammation including anti-inflammatory (IL-4 and IL-10) as well as proinflammatory factors (CRP, TNF-α, IFN-γ, IL-1β, and IL-6), contributing to explain the role of IgG glycosylation on dementia." (PMID 33542243, 2021). "This is consistent with a study showing that a composite measure of circulating inflammatory markers (CRP and tumor necrosis factor-alpha) was negatively correlated with the FA values of the CC body and isthmus in a community sample of 95 subjects older than 70 years of age and without dementia." (PMID 31011488, 2019). "Additionally, TNF-α stimulates the excessive release of harmful reactive oxygen species (ROS) and nitrogen species (RNS) through the activation of nuclear factor kappa B (NF-κB) and the increase in inducible nitric oxide synthase (iNOS) expression in cellular and animal models of AD or dementia." (PMID 38397814, 2024). "Notably, there were many patients who showed elevated TNF-α, but whose carers did not report an acute systemic inflammatory event, suggesting that patients with chronic low-grade conditions have elevated systemic TNF-α, and that this impacts on the progression of underlying dementia." (PMID 25802557, 2015).